L1TD1 (LINE1 type transposase domain containing 1)
Description:
RNA-binding protein which plays a role in the regulation of pluripotency. Preferentially binds to 5'-GAGCGU-3' sequences. Binds to the 3'-UTR of the pluripotency regulator TFCP2L1, stabilizing transcripts and resulting in increased TFCP2L1 mRNA levels.
Synonyms: ECAT11; FLJ10884
Tractability: PROTAC: ubiquitination databases record sites on it.
Gene: Protein-coding gene on chromosome 1 (62,194,257 to 62,235,060, forward strand). Ensembl gene ENSG00000240563.
Subcellular location (Human Protein Atlas): Vesicles
Gene Ontology:
Molecular function: protein binding; sequence-specific mRNA binding
Biological process: 3'-UTR-mediated mRNA stabilization; retrotransposition
Cellular component: ribonucleoprotein complex
Genetic constraint (gnomAD): Loss-of-function variants: 18 observed, 20.68 expected, observed/expected ratio (o/e) 0.87, 90% interval 0.6 to 1.29. The synonymous counts are far from expectation, so gnomAD's model fits this gene poorly and the ratio says little. Missense variants: 1,006 observed, 908.6 expected, observed/expected ratio (o/e) 1.11, 90% interval 1.05 to 1.17. Synonymous variants: 385 observed, 315.1 expected, observed/expected ratio (o/e) 1.22, 90% interval 1.12 to 1.33.
Homologues: Orthologues: chimpanzee L1TD1 (98% identical), macaque L1TD1 (89% identical), dog L1TD1 (59% identical), rat L1td1 (46% identical), mouse L1td1 (44% identical).
Diseases named in the same sentence as L1TD1 in open-access papers:
L1TD1 is named in the same sentence as 25 diseases in open-access papers, as found by Europe PMC text mining. Sharing a sentence is not in itself a finding about the gene and the disease. The quoted sentences say what the papers report.
adenoma (3 papers, 2018 to 2023). A neoplasm arising from the epithelium. "Expression of the L1TD1 gene in our study progressively increased from adenoma to CRC, with the highest expression in CRC with lymph node metastases." (PMID 33670246, 2021). "EPHA4 and L1TD1 follow the third pattern, which higher expression in adenoma and lower in normal and carcinoma." (PMID 30175151, 2018). "And the 6 coincident genes significantly enriched in adenoma and carcinoma were DEFA6, SOX9, ID1, L1TD1, CXCL3, and ODC1." (PMID 36944972, 2023). "In C2 goblet cells, during the process from normal colon to adenoma and from adenoma to carcinoma, several continuously highly expressed genes were found, including DEFA6, SOX9, ID1, L1TD1, CXCL3, and ODC1." (PMID 36944972, 2023). "A bioinformatics study on CRC showed differentially expressed SLITRK6 together with L1TD1 and ST6GALNAC1, and it was downregulated in CRC compared to adenomas using microarray expression analysis." (PMID 33670246, 2021). "The last four genes in our study were downregulated in carcinoma compared to adenoma, and those are EPHA4, KIAA1324, L1TD1, and PCKS1." (PMID 30175151, 2018).
colorectal cancer (3 papers, 2017 to 2024). A primary or metastatic malignant neoplasm that affects the colon or rectum. "A correlation between miR-1303 and L1TD1 was also previously identified in the integrative knowledge base for miRNA-mRNA expression in colorectal cancer." (PMID 33670246, 2021). "In contrast, L1TD1 expression was significantly downregulated in breast carcinomas (p = 0.0253), colorectal carcinomas (p = 0.0224) and in prostate carcinomas (p < 0.0001), but not in head and neck carcinomas, kidney clear cell carcinomas and in hepatocellular carcinomas." (PMID 28093071, 2017).
non-small cell lung carcinoma (3 papers, 2017 to 2025). A group of at least three distinct histological types of lung cancer, including non-small cell squamous cell carcinoma, adenocarcinoma, and large cell carcinoma. "Ectopic expression of L1TD1 also decreased tumor cell viability, proliferation, and the capacity of Non-Small Cell Lung Cancer (NSCLC) cells to form colonies." (PMID 38922530, 2024). "L1TD1 mRNA expression was found to be frequently downregulated in all of the non-small cell lung cancer cell lines compared to healthy human bronchial epithelial cells." (PMID 38922530, 2024). "DNMT inhibitor treatment of non-small cell lung carcinoma (NSCLC) patient-derived cells resulted in reduced cell viability and up-regulation of L1TD1, indicating an epigenetic control of the L1TD1 gene." (PMID 40112032, 2025).
seminoma (3 papers, 2016 to 2025). A radiosensitive malignant germ cell tumor found in the testis (especially undescended), and extragonadal sites (anterior mediastinum and pineal gland). "L1TD1 has previously been shown to be essential for self-renewal of embryonal carcinoma cells and to support the growth of seminoma cells." (PMID 31337362, 2019). "Besides these healthy tissues, L1TD1 expression has also been reported in seminoma, embryonic carcinomas, medulloblastoma, and colon adenocarcinoma." (PMID 31337362, 2019). "Additionally, the L1TD1 gene is also highly expressed in testicular seminoma, and depletion of L1TD1 in seminoma cancer cells influences their self-renewal and proliferation." (PMID 26649052, 2016). "We discovered that, unlike in hESCs and seminomas, L1TD1 was not co-expressed with its interaction partners in colon cancer." (PMID 31337362, 2019). "Interestingly, the high positive correlation observed among L1TD1 and its top 20 interaction partners in seminoma and stem cell data sets (P < 0.0001) was absent in all three colon cancer data sets." (PMID 31337362, 2019).
colon cancer (2 papers, 2017 to 2019). "In the three colon cancer data sets, expression of L1TD1 was associated with samples of low clinical cancer stage, which can perhaps be a reason for its prognostic significance." (PMID 31337362, 2019). "Expression of L1TD1 at high levels in colon cancer cells led us to hypothesize that high expression of L1TD1 in colon cancer might be associated with prognosis." (PMID 31337362, 2019). "Interestingly, our results were in contrast with previous studies, suggesting that in colon cancer, high expression of L1TD1 is linked to better prognosis." (PMID 31337362, 2019). "Our results identify increased expression of L1TD1 as a prognostic marker predicting longer disease-free survival in colon cancer patients." (PMID 31337362, 2019). "Correlation analysis was performed to investigate the role of the interactome of L1TD1 in colon cancer patients." (PMID 31337362, 2019). "Across the three colon cancer microarray data sets, 26.7% of the colon cancer patients were categorized to have high L1TD1 expression." (PMID 31337362, 2019). "Our study of gene expression data from four clinical colon cancer data sets produced promising evidence in support of L1TD1 as a marker for good prognosis in colon cancer." (PMID 31337362, 2019). "Our study identifies LINE-1 type transposase domain containing 1 (L1TD1) as a novel positive prognostic marker for colon cancer." (PMID 31337362, 2019). "Our results emphasize the need for further investigation and validation of L1TD1 as a potential prognostic marker in larger cohorts of colon cancer." (PMID 31337362, 2019). "We identified genes that were co-expressed with L1TD1 in colon cancer patients using Spearman rank correlation." (PMID 31337362, 2019). "In this study, we examined the prognostic value of L1TD1 in colon cancer patients." (PMID 31337362, 2019). "We found L1TD1 as a novel positive prognostic marker for colon cancer." (PMID 31337362, 2019). "We found compelling evidence of L1TD1 being a positive prognostic marker for colon cancer." (PMID 31337362, 2019). "Our findings suggest that L1TD1 is a promising prognostic marker for colon cancer." (PMID 31337362, 2019). "We also investigated genes that were co-expressed with L1TD1 in colon cancer." (PMID 31337362, 2019). "We studied L1TD1 immunoexpression in colon adenocarcinoma tissue sections and analyzed three independent gene expression microarray data sets of colon cancer patients to assess the prognostic significance of L1TD1 in colon cancer." (PMID 31337362, 2019). "Moreover, we determined methylation of SPAG6 and L1TD1 in 5 breast cancer, 2 colon cancer, 2 ovarian cancer, 2 pancreatic cancer as well as 2 head and neck cancer cell lines." (PMID 28093071, 2017). "Kaplan-Meier analysis of 928 samples from the three colon cancer data sets revealed that the colon cancer samples with high L1TD1 expression had longer disease-free survival as compared to those with no/low L1TD1 expression." (PMID 31337362, 2019). "Notably, in medulloblastoma L1TD1 was co-expressed with its interaction partners, whereas our analysis revealed lack of co-expression of L1TD1 with its interaction partners in colon cancer." (PMID 31337362, 2019).
embryonal carcinoma (2 papers, 2019 to 2021). A non-seminomatous malignant germ cell tumor characterized by the presence of large germ cells with abundant cytoplasm resembling epithelial cells, geographic necrosis, high mitotic activity, and pseudoglandular and pseudopapillary structures formation. "L1TD1 has been shown to be associated with RNA binding, renewal of undifferentiated embryonal stem cells and embryonal carcinoma cell lines." (PMID 33670246, 2021).
medulloblastoma (2 papers, 2019 to 2025). A malignant, invasive embryonal neoplasm arising from the cerebellum. "This was further supported by a recent study in medulloblastoma, showing an association of high L1TD1 expression with poor clinical outcome and significant co-expression between L1TD1 and its interaction partner OCT4." (PMID 31337362, 2019). "Our results were in contrast to a previous study on medulloblastoma, where high expression of L1TD1 was linked with poor prognosis." (PMID 31337362, 2019). "In this context, L1TD1 was identified as a possible prognostic marker for medulloblastoma and colorectal tumors, where its expression is highly correlative with malignancy progression." (PMID 40112032, 2025). "In contrast, L1TD1 was shown to be required for cell viability in medulloblastoma." (PMID 40112032, 2025).
germ cell tumor (1 paper, 2025). A benign or malignant, gonadal or extragonadal neoplasm that originates from germ cells. "Apart from early development, L1TD1 is expressed in certain tumors, including germ cell tumors and colorectal cancers." (PMID 40112032, 2025).
lung adenocarcinoma (1 paper, 2017). A carcinoma that arises from the lung and is characterized by the presence of malignant glandular epithelial cells. "However, analyses of gene expression microarray data indicate that low SPAG6 expression is associated with a shorter OS of lung squamous cell carcinoma patients and low L1TD1 expression with a shorter OS of lung adenocarcinoma patients." (PMID 28093071, 2017).
cancer (11 papers, 2015 to 2025). A tumor composed of atypical neoplastic, often pleomorphic cells that invade other tissues. "In cancer, L1TD1 expression is highly correlative with malignancy progression and as such considered a potential prognostic factor for tumors." (PMID 40112032, 2025). "To this end, we activated L1TD1 expression by inducing DNA hypomethylation via deletion of DNMT1 in the nearly haploid human cancer cell line HAP1." (PMID 40112032, 2025). "We report here that L1TD1 deletion in DNMT1-deficient cells led to reduced cell viability and increased apoptosis in HAP1 cancer cells." (PMID 40112032, 2025). "L1TD1 has been described as a good prognosis marker candidate in CRC, but its elevated expression has also been associated with poor prognosis in other cancer types." (PMID 33648461, 2021). "In an attempt to understand the distinctive role of L1TD1 in different cancers, we investigated the co-expression of L1TD1 with its currently known interaction partners." (PMID 31337362, 2019). "L1TD1 expression was higher in the samples from early cancer stages as compared to those from later stages in all the three data sets (P < 0.05), whereas differences between the later stages were typically not statistically significant." (PMID 31337362, 2019). "Among the genes whose preferential expression in tail blastema was confirmed by qRT-PCR, l1td1 is an RNA-binding protein required for self-renewal of human embryonic stem cells and proliferation of cancer cells." (PMID 25775398, 2015). "The domesticated transposon protein L1TD1, derived from LINE-1 (L1) ORF1p, is an RNA-binding protein that is expressed only in some cancers and early embryogenesis." (PMID 40112032, 2025).
tumor (10 papers, 2005 to 2025). "Additionally, significant associations were observed between L1TD1 expression and tumor location or tumor differentiation status (P < 0.0001)." (PMID 31337362, 2019). "Our findings reveal that DNA hypomethylation induces the expression of L1TD1 in HAP1 human tumor cells." (PMID 40112032, 2025). "To gain insight into the regulatory function of L1TD1 in tumor cells, we performed RIP-seq, transcriptome, and proteome analyses in HAP1 cells." (PMID 40112032, 2025). "To address the function of L1TD1 in human tumor cells, we generated a defined human tumor cell model." (PMID 40112032, 2025). "The genes L1TD1 (LINE-1 Type Transposase Domain Containing 1) and SPAG6 (Sperm Associated Antigen 6) are tumor-specifically methylated in NSCLC." (PMID 32299382, 2020). "L1TD1 additionally has been shown to have tumor growth-suppressing properties and seems to be universally methylated and thereby downregulated in NSCLC." (PMID 34991275, 2019). "Differences in SPAG6 and L1TD1 methylation between TU and NL samples were statistically significant (p < 0.0001, respectively) demonstrating that both genes are tumor-specifically methylated." (PMID 28093071, 2017). "Taken together we identified methylation as a potential mechanism for frequent downregulation of SPAG6 and L1TD1 in NSCLCs and suggest a putative role of L1TD1 in tumor cell development." (PMID 28093071, 2017). "Overall, our results demonstrate that SPAG6 and L1TD1 are tumor-specifically methylated in NSCLCs and that DNA methylation is involved in the transcriptional regulation of these genes." (PMID 28093071, 2017). "Two of them, SPAG6 and L1TD1, were selected for detailed investigation of gene expression, gene-specific methylation and potential tumor-cell growth suppressing properties in NSCLCs." (PMID 28093071, 2017). "Because in vitro experiments suggested tumor-cell growth suppressing properties of L1TD1, we additionally performed in vivo studies using immunodeficient mice." (PMID 28093071, 2017). "Tumor suppressors L1TD1 and PARP6, also the specific ESGs of TIME-1, and their methylation may promote tumor proliferation and low immune infiltration." (PMID 33407585, 2021). "Interestingly, we observed significantly smaller tumors induced by pCMV6-L1TD1 compared to pCMV6-ENTRY transfected NCI-H1975 cells indicating that L1TD1 indeed has tumor-cell growth suppressing properties." (PMID 28093071, 2017). "In addition, potential tumor-cell growth suppressing properties of these genes were investigated in in vitro studies and, for L1TD1, also in in vivo xenograft experiments." (PMID 28093071, 2017). "Moreover, in vitro and in vivo experiments showed that L1TD1 has tumor-cell growth suppressing properties in NSCLC cells." (PMID 28093071, 2017). "Furthermore, our results indicate that L1TD1 functions as a tumor cell growth suppressor in NSCLC cells." (PMID 28093071, 2017). "Moreover, in vitro as well as in vivo experiments revealed tumor-cell growth suppressing properties of L1TD1 in NSCLC cells." (PMID 28093071, 2017). "Because of these encouraging results and to further support our hypothesis that L1TD1 has tumor-cell growth suppressing properties, we additionally performed xenograft experiments to investigate the growth of tumors induced by L1TD1-overexpressing and wildtype NSCLC cells." (PMID 28093071, 2017). "Overall, these data suggest that deregulated expression of SPAG6 and L1TD1 may play a role not only in the pathogenesis of NSCLCs but also in tumors of other entities and that expression of these 2 genes differs between certain tumor types." (PMID 28093071, 2017). "Genes that are tumor specifically methylated in LC, specifically NSCLC, further include SPAG6 and L1TD1." (PMID 34991275, 2019).
tumor (continued). "All these tumor cell lines were found to be SPAG6 and L1TD1 methylated with percentages of methylation ranging between 71% (SK-OV3 cells) and 98% (FaDu cells) for SPAG6 methylation and between 88% (BxPC-3 cells) and 100% (FaDu cells) for L1TD1 methylation." (PMID 28093071, 2017). "Our results demonstrate that tumor-specific methylation of SPAG6 and L1TD1 is a frequently occurring event in NSCLCs and they suggest that methylation plays an important role in the transcriptional regulation of these genes." (PMID 28093071, 2017). "To investigate potential tumor cell - growth suppressing properties of L1TD1, we stably transfected NCI-H1975 cells with a pCMV6-L1TD1 expression vector, with a pCMV6-ENTRY control vector as well as with a constructed pCMV6-GFP vector." (PMID 28093071, 2017). "Frequent tumor-specific DNA methylation of SPAG6 and L1TD1 was detected when we analysed TU and corresponding NL samples of NSCLC patients." (PMID 28093071, 2017). "We observed frequent downregulation of SPAG6 and L1TD1 mRNA expression in primary tumor ﻿(TU) samples compared to corresponding non-malignant lung tissue (NL) samples of NSCLC patients." (PMID 28093071, 2017). "In addition, xenograft tumors with NSCLCs overexpressing L1TD1 showed decreased tumor growth, suggesting a negative impact of L1TD1 expression on tumor viability." (PMID 40112032, 2025). "Since SPAG6 and L1TD1 were found to be frequently methylated and downregulated in NSCLC cells and are located in chromosomal regions where frequent LOH was observed, we hypothesized that these genes may have tumor-cell growth suppressing properties." (PMID 28093071, 2017).
L1TD1 also shares sentences with these, for which no sentence is quoted: ovarian carcinoma (2 papers); adenocarcinoma (1); breast carcinoma (1); colon adenocarcinoma (1); head and neck carcinoma (1); hepatocellular carcinoma (1); infection (1); kidney clear cell carcinomas (1); lung squamous cell carcinoma (1); Obesity (1); pancreatic cancer (1); prostate carcinoma (1); squamous cell carcinoma (1); testicular seminoma (1).